TOR4A (torsin family 4 member A)
Synonyms: C9orf167; FLJ20245
Tractability: Antibody: its Gene Ontology location is reachable by antibodies, with high confidence; UniProt predicts a signal peptide or a membrane-spanning region. PROTAC: ubiquitination databases record sites on it; its protein half-life has been measured.
Gene: Protein-coding gene on chromosome 9 (137,274,854 to 137,282,641, forward strand). Ensembl gene ENSG00000198113.
Subcellular location: Membrane
Subcellular location (Human Protein Atlas): Nucleoplasm
Pathways (Reactome):
Hemostasis: Platelet degranulation
Gene Ontology:
Molecular function: ATP binding; ATP hydrolysis activity
Cellular component: endoplasmic reticulum lumen; extracellular region; nuclear envelope; platelet alpha granule lumen; cytoplasm; endomembrane system; membrane
Genetic constraint (gnomAD): Loss-of-function variants: 13 observed, 6.96 expected, observed/expected ratio (o/e) 1.87, 90% interval 1.11 to 1.96. That is too few expected variants to judge how well the gene tolerates losing a copy. Missense variants: 640 observed, 484.22 expected, observed/expected ratio (o/e) 1.32, 90% interval 1.24 to 1.41. Synonymous variants: 362 observed, 235.01 expected, observed/expected ratio (o/e) 1.54, 90% interval 1.41 to 1.68.
Homologues: Orthologues: chimpanzee TOR4A (99% identical), macaque TOR4A (95% identical), pig TOR4A (85% identical), guinea pig TOR4A (78% identical), rat Tor4a (78% identical), mouse Tor4a (78% identical), tropical clawed frog tor4a (46% identical), zebrafish tor4aa (41% identical), zebrafish tor4ab (38% identical), Caenorhabditis elegans ooc-5 (16% identical), Drosophila melanogaster Torsin (14% identical), Caenorhabditis elegans tor-1 (13% identical), and 1 more. Paralogues in human: TOR1A (18% identical), TOR1B (18% identical), TOR2A (17% identical), TOR3A (17% identical).
Diseases named in the same sentence as TOR4A in open-access papers:
TOR4A is named in the same sentence as 3 diseases in open-access papers, as found by Europe PMC text mining. Sharing a sentence is not in itself a finding about the gene and the disease. The quoted sentences say what the papers report.
Dystonia (1 paper, 2021). An abnormally increased muscular tone that causes fixed abnormal postures. "We also found a CpG site upstream of TOR4A (Torsin family 4 member A), which is associated with dystonia." (PMID 34262470, 2021).
glioma (1 paper, 2025). A benign or malignant brain and spinal cord tumor that arises from glial cells (astrocytes, oligodendrocytes, ependymal cells). "DNER, a noncanonical Notch ligand, was found to suppress glioma growth by inhibiting the oncogene TOR4A and hindered the growth and induced differentiation of GBM-derived neurospheres." (PMID 39874307, 2025).
tumor (1 paper, 2025). "For the downregulated genes, Id1, Tor4a, Fam83d, Chst12, Fhod1, Sapcd2, and Gas2l3 are known as proliferative and metastatic oncogenes contributing to tumor progression." (PMID 40231790, 2025).